FOXP3 (forkhead box P3)
Diseases named in the same sentence as FOXP3 in open-access papers (continued):
Sharing a sentence is not in itself a finding about the gene and the disease.
preeclampsia (19 papers, 2013 to 2026). Preeclampsia is a hypertensive disorder of pregnancy that is characterized by new-onset hypertension with proteinuria presenting after 20 weeks of gestation, and depending on mild or severe forms may initially present with severe headache, visual disturbances, and hyperreflexia. "To evaluate the potential influence of Foxp3 polymorphism on preeclampsia (PE) susceptibility, we conducted a case-control study in Han Chinese women." (PMID 23560055, 2013). "Women with preeclampsia had significantly lower percentages of CD4+FOXP3+ T-regs and concluded that a deficiency of T-regs may play a role in the development of PE." (PMID 37700972, 2023). "In addition to this relationship, FOXP3 rs3761548 polymorphism was also tested for its association with preeclampsia." (PMID 36362759, 2022). "Foxp3 deficiency is also associated with preeclampsia and unexplained miscarriage." (PMID 32057179, 2020). "Accordingly, women with preeclampsia (PE) have a higher expression of Th1/Th17 factors (T-bet, RORc) and a lower expression of Treg/Th2 factors (FoxP3, GATA-3) than in normal pregnancies." (PMID 41156157, 2025). "Th1/Th2 intermediate and FOXP3+ Treg subsets showed altered gene expression in preeclampsia (PE) compared to healthy late gestation." (PMID 38774869, 2024). "Similarly, when only immunological parameters were considered, CD4+ FOXP3+ % was significant (B = -0.012, Exp(B) = 0.989, Cox & Snell R2 = 0.641, p < 0.001) in detecting preeclampsia." (PMID 37700972, 2023). "We found that frequencies of cord blood CD4+Foxp3+Helios+ thymic-derived natural Tregs (nTreg) were also significantly lower in preeclampsia (p = 0.035, unpaired t-test), especially in those who did not receive steroid treatment (p = 0.01, one-way ANOVA with Dunnett’s multiple comparisons test)." (PMID 31292453, 2019). "The decreasd expression of Foxp3 in preeclampsia demonstrates that the reduction of Tregs numbers may result in the imbanance of immunologic tolerance between the mother and fetus,thereby participating in the pathogenesis of preeclampsia." (PMID 23560055, 2013). "Between normal pregnancy and preeclampsia, there is a significant difference only in CD4+FOXP3+Tregs." (PMID 39328700, 2024). "In the group of women with preeclampsia compared to the group with gestational hypertension, significantly higher percentages of CD4+CD25+FoxP3+ cells (p = 0.03) and percentages of CD4+CD25+FoxP3+ cells expressing the OX40 antigen (p = 0.001) were observed." (PMID 37887878, 2023). "Therefore, the aim of our study was to assess the population of Treg (CD4+CD25+FoxP3+) and Th17 lymphocytes, as well as the intracellular expression of IL-17A, IL-17F, IL-21, and IL-22 in women with PIH (including preeclampsia)." (PMID 41156157, 2025). "CD4+FOXP3 was significantly lower in the preeclampsia group compared to normal pregnancy and non-pregnant fertile women." (PMID 39328700, 2024). "Moreover, for the preeclampsia group, no staining of Foxp3 was observed in these tissues." (PMID 31292453, 2019). "Between the non-pregnant fertile group and preeclampsia, there is a significant difference in lymphocytes and CD4+FOXP3+Tregs." (PMID 39328700, 2024). "This one-dimensional Th1/Th2 paradigm can, however, not fully explain the immunological changes observed during preeclampsia and recent work has expanded the dichotomy to include the Th17 phenotype and a subset of CD4+ T cells known as CD25+ Forkhead box P3 gene (Foxp3+) Tregs." (PMID 30079067, 2018).
uveitis (19 papers, 2012 to 2025). An inflammatory process affecting a part of or the entire uvea. "The discrepancy between Rorc and Foxp3 CNVs and susceptibility to these two uveitis entities may be due to the different features of these two diseases." (PMID 25873156, 2015). "A2Ar induction of PD-1+FoxP3+ Tregs in uveitis patients was similar compared to healthy controls, but was significantly reduced with melanocortin stimulation." (PMID 31729418, 2019). "We therefore assayed for the abundance of PD-1+FoxP3+CD25+CD4+ Tregs cells in PBMCs of uveitis patients and healthy controls and determined if stimulation of the melanocortin-adenosinergic pathway induced Tregs." (PMID 31729418, 2019). "In mice that already developed uveitis, depletion of Foxp3+ Tregs at the peak of disease prevented resolution, and depletion after resolution induced a relapse, indicating that Foxp3+ Tregs naturally bring about and maintain resolution of EAU." (PMID 30356688, 2018). "T-bet, GATA3, RORγt, and Foxp3 are master transcription factors for the important Th cell subsets of uveitis, including Th1, Th2, Th17, and Treg cells." (PMID 30254507, 2018). "In vitro-stimulation of intraocular cells with both, antigen or mitogen, resulted in an increase of Foxp3-expressing T cells, which was higher in cells from R14-induced uveitis." (PMID 23155443, 2012). "Regulatory T cells are expected to be responsible for preventing relapses of intraocular inflammation, and thus we have looked for Foxp3- and IL-10-expressing cells in the eyes and peripheral lymph nodes during monophasic and relapsing experimental uveitis." (PMID 23155443, 2012). "In addition, in the TCR transgenic mice with uveitis, a substantial fraction of the P2-tetramer binding cells in the retina expressed Foxp3-EGFP." (PMID 38261611, 2024). "Depletion of Foxp3+ Tregs in uveitis leads to more severe uveitis during EAU." (PMID 37878302, 2023). "The number of TIGIT+FoxP3+ Tregs was significantly decreased in PBMCs from patients with uveitis." (PMID 35720417, 2022). "Depletion of Foxp3+ Tregs caused the mice to develop more severe uveitis upon IRBP challenge, indicating that preexisting (likely thymic-derived) Tregs raise the threshold of susceptibility to uveitis." (PMID 30356688, 2018). "Also Foxp3+ T cells were significantly elevated (p<0.05) in eyes during late remission of PDSAg-induced uveitis, indicating the extended presence of elevated numbers of regulatory cells in the eyes of non-relapsing EAU." (PMID 23155443, 2012). "That similar numbers of Foxp3-expressing cells were found in both types of EAU indicates that Foxp3 might not be the only factor that is required to prevent relapsing uveitis." (PMID 23155443, 2012). "Intraocular Foxp3+/TCR-αβ+ cells of R14-induced EAU increased 3.6fold after R14- and 4.3fold after Con A-stimulation, indicating a weaker antigen-specific response of Foxp3+ cells in the monophasic type of uveitis that is thought to be less stringently regulated." (PMID 23155443, 2012). "However, when we quantified the number of PD-1+FoxP3+ Tregs as we found to be the suppressive Treg population in mice, we found a significant decrease in PBMCs from uveitis patients compared to controls when stimulated through the melanocortin pathway, but not when stimulated through A2Ar." (PMID 31729418, 2019). "Previous studies found the dysregulations of TBX21/GATA3 and Rorc/Foxp3 ratios in uveitis patients with neuro-BD20, suggesting that a dysregulated function of these T cell subsets may lead to immune imbalance, proliferation and activation of pathogenic CD4+ T cells subsequently leading to uveitis." (PMID 25873156, 2015). "Interestingly, in quiescent eyes after subsiding of intraocular inflammation, significantly more Foxp3+ cells were found in eyes of PDSAg- compared to R14-induced uveitis, suggesting that these cells might indeed have a regulatory phenotype." (PMID 23155443, 2012).
uveitis (continued). "CD25+FoxP3+ Treg, FoxP3+TIGIT+ Treg, and FoxP3+T-bet+ Treg were also observed to increase as disease resolved in patients with active uveitis." (PMID 29774027, 2018). "Another study compared Treg levels in active and inactive uveitis patients and found that patients in remission on treatment (n = 25) had significantly increased levels of CD4+CD25+FoxP3+ Treg compared with active patients on treatment (n = 6)." (PMID 29774027, 2018). "In our study, the frequency of CD4+CD25+Foxp3+ Treg cells and the expression of Foxp3 mRNA were significantly decrease in AAU, which was consistent with previous studies in human uveitis." (PMID 28091550, 2017). "Our previously published work showed that under normal conditions in vivo the RPE does not express FoxP3, while it does upregulate FoxP3-expression in uveitis, suggesting a correlation with stress situations like ocular inflammation." (PMID 36273134, 2022). "Results further showed that TIGIT+FoxP3+ Tregs are induced by stimulation of adenosine 2A receptor (A2Ar) in healthy volunteers, but not in patients with uveitis." (PMID 35720417, 2022). "A study involving 50 AU patients and 10 healthy subjects revealed that there were significantly higher frequencies of CD4+CD25+FoxP3+ Treg, TIGIT+ Treg, and T-bet+ Treg and Treg/Th1 ratio in the clinical remission subjects compared with active patients of uveitis." (PMID 35720417, 2022). "Based on these observations, we propose that FoxP3 expression and its translocation to the nucleus in situations of enhanced stress is essential for the resistance against age-dependent changes or RPE damage, or acute or chronic inflammation like in uveitis." (PMID 36273134, 2022). "However, in disease conditions such as experimental uveitis or laser-induced CNV, FoxP3 abundantly localized to the nucleus, which is suggestive of an increased activity of the transcription factor on gene expression in the RPE." (PMID 36273134, 2022). "Normally, the RPE does not express FoxP3 but rather initiates its expression under conditions of stress, as occurs in experimental uveitis." (PMID 36273134, 2022). "FOXP3 and TBX21 were increased in our cases compared to healthy controls, which correlates with data revealing increased expression of these transcription factors in VKH patients during an active uveitis episode." (PMID 33384688, 2020). "FoxP3 expression was not significantly different between healthy controls and uveitis patients in PBMCs at rest." (PMID 31729418, 2019). "The number of PD-1+FoxP3+CD25+CD4+ Tregs trended higher in the uveitis cohort under resting conditions, but was not statistically significant." (PMID 31729418, 2019). "Low or absent levels of FoxP3 mRNA are found in Tregs from patients with severe, recalcitrant uveitis." (PMID 29774027, 2018). "Higher frequencies of FoxP3+, CD4+ Tregs were found in intestinal lymphoid tissues (cecal and colonic LPL) in SCFA-treated EAU mice than in the EAU control mice at 1 week post-immunization, prior to the onset of uveitis (NaCl 1w: 59.9 ± 5.6%vs." (PMID 28924192, 2017). "FoxP3 was identified in the RPE of rat eyes with uveitis, but not in RPE cells of healthy control retinas." (PMID 28663750, 2017). "Stimulation of A2Ar stimulation had some enhancement of the PD-1+FoxP3+CD25+CD4+ subset in healthy controls and uveitis patients but was not significantly different between the two groups." (PMID 31729418, 2019). "Our data show that hypomethylation at FOXP3 TSDR, FOXP3 promoter, and TIGIT CpG sites and higher levels of TIGIT+ Tregs are associated with clinical remission, and may have value in determining remission, of relapsing and remitting sight-threatening non-infectious uveitis." (PMID 29774027, 2018).
autoimmune hepatitis (18 papers, 2011 to 2025). Hepatitis caused by autoantibodies. "In this study, we developed exosomes modified to specifically bind CD4 molecules, creating engineered exosome-associated AAV vectors carrying the Foxp3 gene for autoimmune hepatitis treatment." (PMID 40284659, 2025). "Contrary to our observations, patients with active autoimmune hepatitis showed lower levels of Tregs and expressed lower FOXP3 levels, and functional analysis revealed a lower ability to inhibit target cell proliferation." (PMID 32664587, 2020). "Moreover, the number of FoxP3-expressing Tregs was markedly reduced in affected portal tracts in PBC livers when compared with autoimmune hepatitis (AIH) and chronic hepatitis." (PMID 37325634, 2023). "Interestingly, defective accumulation of regulatory T cells (Tregs) expressing forkhead box protein P3 (FOXP3) was evident in this case with hepatic irAEs as compared with typical cases with autoimmune hepatitis." (PMID 33665689, 2021). "Indeed, in vitro studies stimulating PBMCs or liver infiltrating lymphocytes from patients with autoimmune liver diseases with low doses of IL-2 showed improved survival and function of Foxp3+ TREG." (PMID 34463867, 2021). "Exposure of PBMCs from patients with autoimmune liver diseases, including AIH, to very-low-dose Proleukin, used at less than 5 IU/ml, resulted in phosphorylation of STAT-5 and increased levels of CTLA-4 and FOXP3 in the Treg subset." (PMID 34650567, 2021). "As a drug, FTY720 was used to treat autoimmune hepatitis, inhibits Th1 cells to produce IFN-γ, activates Foxp3+ Tregs by recruiting MDSCs, and reduces liver damage in CIH." (PMID 30647537, 2018). "Patients with CHB and CHC as well as those with the other hepatic diseases (NAFLD, autoimmune hepatitis, PBC, and MTX-related hepatotoxicity) presented a statistically significant increase of Foxp3 mRNA levels compared to normal controls." (PMID 21772667, 2011). "Most intriguing is the finding that increased Foxp3 expression, and therefore nTregs intrahepatic accumulation, characterizes not only viral hepatitis but also to an equal degree, NAFLD as well as autoimmune hepatitis, PBC and MTX-related hepatotoxicity." (PMID 21772667, 2011). "Similar to organ rejection, graft vs. host disease in liver tissue had similar immune expression to hepatis irAEs with infiltration of CD8+ T cells and defective accumulation of regulatory T cells expressing forkhead box p3 (FOXP3), but not in those from patients with autoimmune hepatitis." (PMID 36358686, 2022).
follicular lymphoma (18 papers, 2006 to 2025). Follicular lymphoma is a form of non-Hodgkin lymphoma characterized by a proliferation of B cells whose nodular structure of follicular architecture is preserved. "Additionally, a recent study demonstrated that high numbers of tumor infiltrating FOXP3-positive regulatory T cells are associated with improved survival in follicular lymphoma." (PMID 17166272, 2006). "For instance, in patients with follicular lymphoma, an increase in the number of tumor-infiltrating Foxp3+ T cells correlates with improved survival rates and decreased follicular lymphoma counts." (PMID 39000453, 2024). "Still, we could not detect any FOXP3+ cells, although Tregs were provable in human tonsils and follicular lymphoma, while not on PCNSL tissue." (PMID 32010141, 2019). "Therefore, in contrast to previous observations in follicular lymphoma, no characteristic architectural pattern of FOXP3+ cells was found in gastric MALT lymphoma." (PMID 23284739, 2012). "To investigate whether the inter‐follicular density of CD8+FOXP3+ and co‐localization of CD8+FOXP3+ with CD4+CD8+ are predictors of TTP independent of follicular lymphoma international prognostic index (FLIPI), we applied multivariate Cox regression analysis." (PMID 35451108, 2022).
Insulin resistance (18 papers, 2011 to 2023). Increased resistance towards insulin, that is, diminished effectiveness of insulin in reducing blood glucose levels. "Consistent with the decrease in body weight, fasting plasma insulin, fasting blood glucose, and insulin resistance (IR) were significantly reduced in IL-10fl/fl Foxp3-Cre+ mice compared with WT controls." (PMID 33351782, 2021). "In the insulin resistance control group, the expression levels of IL-6, RORγt, and IL-17 increased, whereas those of IL-10, FoxP3, and CD4+CD25+Treg decreased." (PMID 31218568, 2019). "In this study, we elucidated the role of CD4+CD25+Foxp3+ Tregs to insulin resistance in a CBA/J mice model of HT is established by the administration of iodine and induction of immune response to thyroid globulin." (PMID 29541033, 2018). "Previous work has shown that obese patients with insulin resistance have decreased HELIOS but increased FOXP3 mRNA expression in visceral adipose tissue." (PMID 24962627, 2014). "This study also showed that interleukin-10 (IL-10), produced by these Foxp3 Treg cells, inhibited tumor necrosis factor-alpha (TNFα)-induced expression of proinflammatory mediators and insulin resistance in 3T3-L1 adipocytes." (PMID 23671849, 2013). "Loss-of-function/depletion experiments and gain-of-function/adoptive transfer experiments, demonstrate that these Foxp3+ cells are responsible for controlling the inflammation in the fat tissue and development of insulin resistance." (PMID 24069022, 2013). "In normal mice, Foxp3+ cells can be found in the adipose tissue, but in the obese insulin-resistance mouse models or mouse fed with high fat diet, the number of these cells is reduced." (PMID 24069022, 2013). "Another study demonstrated that regulatory CD4+ T cells expressing the transcription factor Foxp3 (Treg cells) are predominately found in the abdominal fat of normal mice but are reduced in the abdominal fat in mouse models of insulin resistance." (PMID 23671849, 2013). "In contrast, consistent with our findings on the putative importance of visceral adipose tissue CD4+Foxp3+ T cells in insulin resistance, the proportions were similar in the SC WAT depot in both genotypes." (PMID 23562076, 2013). "When Th1 statically overwhelms CD4+ FoxP3- Tregs, weight gain and insulin resistance are reversed." (PMID 36776877, 2023). "To determine whether the decrease in the Treg fraction mediates COX-2 deficiency–induced insulin resistance, we adoptively transferred CD4+Foxp3+ Tregs from Foxp3-eGFP mice into either COX-2–KO mice or control littermates." (PMID 35260536, 2022). "So CD25+Foxp3+Tregs related to the insulin resistance in HT model mice." (PMID 29541033, 2018). "We also investigated the mechanism by which CD4+CD25+Foxp3+ Tregs decreases insulin resistance." (PMID 29541033, 2018). "Administration of anti-CD25 antibodies just partly abolished beneficial effects from CD25+Foxp3+ Tregs, so we hypothesized that CD25+Foxp3+ Tregs in VATs might more important to insulin resistance in HT." (PMID 29541033, 2018). "The percentage of peripheral CD4+CD25+Foxp3+ Tregs is decreased in the patients with type 2 diabetes mellitus and the accumulation of Tregs in adipose tissue plays an important role in reducing obesity related insulin resistance in mice." (PMID 29541033, 2018). "Similarly, oral administration of anti-CD3 antibody in conjunction with oral GC in ob/ob obese mice increased Foxp3+ T cells and decreased CD11b+F4/80+ macrophages in adipose tissue, resulting in decreased adipose inflammation and reversal of insulin resistance." (PMID 30323806, 2018). "In previous researches, cytokines and inflammation in adipose tissue are important to insulin resistance in T2DM, so changed level of CD25+Foxp3+ Tregs might relate to insulin resistance through cytokines in HT." (PMID 29541033, 2018).
Insulin resistance (continued). "The induction of IL-10 expression in the adipose tissue might promote Foxp3+ Treg expansion and suppress liver inflammatory cytokine expression and plasma DPP4 activity that may ultimately lead to mitigated insulin resistance and glucose intolerance in diabetic mice." (PMID 35883204, 2022). "Since anti-CD25 treatment selectively depletes CD25+Foxp3+ Treg cells in peripheral blood but not in VAT, the finding supports a potential specific role for VAT Treg cells in improving insulin resistance in HT." (PMID 30323806, 2018).